ENSG00000206731
Synonyms: LOC124906143
Gene: Small nucleolar RNA gene on chromosome 2 (27,642,043 to 27,642,169, reverse strand). Ensembl gene ENSG00000206731.
Gene Ontology:
Biological process: RNA processing
Cellular component: nucleolus
Homologues: Paralogues in human: SNORA36B (86% identical), SNORA36C (80% identical), SNORA36A (79% identical).